IL1B (interleukin 1 beta)
Diseases named in the same sentence as IL1B in open-access papers (continued):
Sharing a sentence is not in itself a finding about the gene and the disease.
tumor (continued). "As one of the most abundant cell types in the tumor microenvironment, the activated CAFs modulate the inflammatory microenvironment by secreting pro-inflammatory cytokines including IL-6, IL-8, and IL-1β and play a key role in depositing and the ECM." (PMID 33322216, 2020). "Macrophage, a major component of tumor immune microenvironment, is a potent producer of IL-1β and IL-23." (PMID 32649314, 2020). "LAB treatment increased IL-1β secretion in tumour tissue whereby the DMH+P group (460.2 ± 53.5 pg/mL) was higher than those in the cancer control (401.1 ± 56.9 pg/mL), but without statistical significance." (PMID 32168834, 2020). "As expected, DCs responded to bacteria treated tumor cells with significant increase in cytokines secretion, including IL-1β, IL-6, MCP-1, and TNF-α." (PMID 33643911, 2020). "Different types of cell factors, such as vascular endothelial growth factor (VEGF), epidermal growth factor (EGF), and interleukin-1β (IL-1β), are released during platelet activation and promote tumor growth and angiogenesis." (PMID 31768743, 2020). "DHA significantly inhibited the activation of inflammasome and reduced IL-1β production in the microenvironment of Hep-2 cell xenograft tumor in nude mice." (PMID 32577124, 2020). "Giving IL-1β and/or IL-23 increased cell proliferation in 4T1 tumor, which was reversed by concurrent use of an IL-22 neutralization antibody." (PMID 32649314, 2020). "In Ghsr+/+ animals, protein level for the pro-inflammatory cytokines Interleukin (IL)-1β in iWAT were increased in tumor-bearing mice and ghrelin prevented this increase." (PMID 32934774, 2020). "IL-1β blockade combined with anti-PD-1 reduced orthotopic tumor weight and improved CD8 T cell infiltration." (PMID 33584701, 2020). "The pro-inflammatory cytokines TNF-α and IL-1β are robustly involved in HCC tumor invasion, angiogenesis, and metastasis." (PMID 33718121, 2020). "Treatment with pyrazinib (P3) significantly reduced the secretion of IL-1β from OAC treatment-naïve tumour biopsies (p = 0.0377)." (PMID 32694701, 2020). "IL-1β, as one of the most potent pro-inflammatory cytokines, is generated by tumor cells and immune cells, such as macrophages, in tumor microenvironment." (PMID 32547321, 2020). "The mature secreted IL-1β is tightly involved in human tumor progression, tumor angiogenesis, invasion, and metastasis." (PMID 32397236, 2020). "This allows the activation of the NLRP3 inflammasome, the production of IL-1β, leading to tumor progression and lung metastasis." (PMID 32635472, 2020). "Since IL1β is a secreted protein and the tumor samples were rinsed before analysis, the western blot showed a modest protein upregulation of approximately 1.2-fold and did not approximate the levels of the mRNA expression change." (PMID 32973969, 2020). "As a pleiotropic pro-inflammatory cytokine, IL-1β is involved in various malignant processes, including upregulating key oncogenic players and maintaining tumor immunosuppressive microenvironment." (PMID 32899791, 2020). "This was accompanied by increased expression of cytokines evaluated by flow cytometry, TNFα, and IFNβ in tumor cells and IL1β and IFNβ in macrophages, which can alter the TME and mediate off-target effects (bystander or abscopal effects)." (PMID 33202881, 2020). "Because IL-1β and IL-23 are upstream cytokines in regulating production of IL-22, we tested the impact of IL-1β and IL-23 on tumor growth." (PMID 32649314, 2020). "In melanoma cells, both IL-1α and IL-1β can promote tumor angiogenesis by activating NF-κB signaling pathways to induce the expression of IL-6, IL-8, intercellular adhesion molecule-1, and tissue factor." (PMID 32993787, 2020). "IL-1β is known to act as an inhibitor of tumor apoptosis via the induction of signal transducer and activator of transcription 3 (STAT3)." (PMID 32069807, 2020). "Pro-inflammatory cytokines IL-1β, IL-6 and IL-8 are expressed in the tumor microenvironment and promote tumor growth." (PMID 33235296, 2020).
tumor (continued). "Because an increased expression of NLRP3, ASC, Caspase-1, IL-1β and IL-18 proteins is observed in tumor tissues from Tgfbr1/Pten 2cKO HNSCC mice, there is a rationale for testing the NLRP3 inflammasome inhibitor, MCC950 in this model." (PMID 33261061, 2020). "During the defense against tumors, immune cells produce pro-inflammatory cytokines such as TNF-α, IL-6, and IL-1β, and tumor-specific T cells produce perforin and granzyme B to clear tumor cells." (PMID 33299138, 2020). "IL1B is produced by high malignancy ccRCC cells and its high expression has been shown to promote tumor aggressiveness." (PMID 33371886, 2020). "Tumor metastasis is usually associated with abnormal expression of cytokines, especially CXCL12, VEGF, IL1β, and IL6, while CAFs can promote tumor growth and invasion via a plethora of active factors." (PMID 31636361, 2020). "This gives rise to the second possible explanation for the divergent effects of IL-1β; that is, perhaps it relies on the T cell subtypes present in the tumor." (PMID 32635472, 2020). "IL-1β damages inflammatory tissues and stimulates tumor invasion by creating a suitable microenvironment for angiogenesis." (PMID 32156252, 2020). "This leads to IL-1β release from cancer cells, and the use of anakinra in combination with cisplatin was shown to achieve decreased tumor growth in mice." (PMID 32635472, 2020). "We first assessed the immunofluorescence intensity of selected inflammasome components (NLRP1, NLRP3, NLRP6, AIM2, ASC, Caspase-1, IL-1β and IL-18) in tumor cells compared to normal epithelial cells, for each patient." (PMID 33255437, 2020). "IL-1β and the vascular endothelial growth factors (VEGFs) are the main factors responsible in establishing and maintaining tumor-mediated angiogenesis." (PMID 32825489, 2020). "Colitis-associated cancer was higher in NLRP3 knockout mice models; the increased tumor burden was correlated with attenuated levels of tumor IL-1β and IL-18." (PMID 31923221, 2020). "It has been shown that the tumor microenvironment is enriched with various soluble mediators, including IL-6, TGFβ, IL-1β, and IL-23, which collectively promote Th17 differentiation via induction of master transcription factor RORγ5,6." (PMID 32770025, 2020). "Within mammalian immune responses and cancer, COX-2 expression is upregulated by both pro-inflammatory cytokines, such as IL-1β, and tumour promoters, such as Ras." (PMID 32325966, 2020). "Volumes of tumors generated from IL-1β-stimulated cells were much larger than those generated from untreated tumor cells (P = 0.020)." (PMID 32547321, 2020). "CCR6 signaling also promotes murine transplantable colon cancer by recruiting macrophages to the TME through a CCL2-CCR6 axis, which results in the release of IL-1β, IL-6, and TNFα, further enhancing tumor progression." (PMID 32733461, 2020). "Proinflammatory cytokines produced in the tumor microenvironment, including IL-1β, IL-6 and IL-8, play critical roles in promoting HCC metastasis." (PMID 32206125, 2020). "For example, in murine models of pancreatic ductal adenocarcinoma, neutralization of tumor-derived IL-1β enhances CTL-infiltration and ameliorates the response to anti-PD-1 immune checkpoint blockade." (PMID 32733461, 2020). "IL-1β stimulation of tumor cells upregulate CXCL13 expression and recruit PD-L1+ regulatory B cells (Bregs)." (PMID 33584701, 2020). "Usually, IL-1β has a pro-tumor role but in some cases, depending on the tumor type or the treatments used, it can act as an anti-tumor cytokine." (PMID 33261061, 2020). "Tumoricidal macrophages are critical in promoting tumor killing and apoptosis through the release of cytotoxic factors and also enhance the production of pro inflammatory cytokines, such as IL-1β and TNF-α." (PMID 33036138, 2020). "In different murine cancer types, this placlitaxel-induced macrophage IL-1β secretion slightly reduced the primary tumor, while promoting metastasis, suggesting a dual role for this drug." (PMID 32635472, 2020).
tumor (continued). "Overexpression of the IL-1 agonists IL-1a and IL-1b has been shown to promote tumor invasiveness and metastasis by inducing the expression of angiogenic genes and growth factors." (PMID 32894202, 2020). "Within the tumor, IL-1β is produced and secreted by various cell types, such as immune cells, fibroblasts, or cancer cells." (PMID 32635472, 2020). "Braun and collaborators demonstrated that tumor-bearing mice have markedly increased hypothalamic levels of IL-1β." (PMID 33291708, 2020). "As expected, the injection of HCC827-derived L-MPs facilitated tumor growth, concomitant with increased IL-1β levels in tumor tissue." (PMID 31649305, 2020). "IL-1β stimulates dendritic cells (DCs) activation and tumor antigen presentation to CD4+ and CD8+ T lymphocytes, thus promoting an efficient antitumor immune response." (PMID 33212982, 2020). "Inhibition of IL-1β was shown to attenuate tumour growth and invasion and ameliorate treatment resistance." (PMID 32694701, 2020). "Mice deficient in the IL-1 receptor-related molecule SIGIRR show increased tumor growth, while tumor-infiltrating myeloid cells produce high levels of IL-1β and IL-6 that promote tumorigenesis." (PMID 32670290, 2020). "This demonstrates that IL-1β is required for instigating tumour-promoting inflammation during early tumourigenesis in mice." (PMID 32325966, 2020). "The expression level of IL-1B was increased in tumor samples when compared with controls (p < 0.001)." (PMID 32527212, 2020). "mRNA levels of IL‐1β in the tumour were decreased in IL‐1R−/− compared with wild‐type mice (P = 0.015)." (PMID 32049447, 2020). "In this case, tumor-released IL-1β helps therapeutic treatments to inhibit tumor growth by recruiting neutrophils at the tumor site." (PMID 32635472, 2020). "Secondly, CD11b+ Ly6G+ neutrophils expedite extravasation of tumor cells through the secretion of IL1β and MMPs." (PMID 33101283, 2020). "In tumor microenvironment, IL-1β contributes to epithelial-mesenchymal transition, which is related to drug tolerance in HNSCC." (PMID 32577124, 2020). "In contrast, in tumor cell lines where NLRP3 activation and, IL-1β and IL-18 secretion are high, although Nigericin triggers initial tumor cell death, cells recover and tumors remain active." (PMID 33613529, 2020). "In BC, IL-1 and IL-1β have been reported to induce tumorigenesis and bone metastasis by regulating the tumor microenvironment." (PMID 32796696, 2020). "At the tumor site, low-level IL-1β expression usually induces immunosuppression at the early stage of disease, but high-level IL-1β usually leads to cell invasion." (PMID 33488930, 2020). "Tumor size was also increased by giving both IL-1β and IL-23, an effect reversed by concurrent use of an IL-22 neutralization antibody." (PMID 32649314, 2020). "Accumulating data demonstrate that IL1B promotes tumor progression and contributes to poor prognosis." (PMID 33168816, 2020). "The sphere formation capability of tumor cells subjected to IL-1β stimulation and ID1 silence was significantly reduced (P < 0.05, vs. all other groups)." (PMID 32547321, 2020). "In the tumor microenvironment, tumor cells also produce IL-1β and act on other cells through autocrine function, thereby avoiding apoptosis and promoting proliferation and invasion." (PMID 33488930, 2020). "IL-1β also drives tumor fibrosis and cancer cell proliferation, survival and chemoresistance in PDAC through the IRAK4-NFκB pathway." (PMID 32760726, 2020). "On the contrary, treatment by irradiation or cisplatin increases tumor cell production of IL-1β, which recruits neutrophils." (PMID 32635472, 2020). "In a study addressing not only TNFα but also IL-1β, the two cytokines were shown to increase tumor cell proliferation in a metastasis-suppressed model of a TNBC cell line and in combination with IL-6 and CXCL8 also of luminal-A cells." (PMID 33585241, 2020).
tumor (continued). "IL-1β is abundant at tumor sites, indicating that it is involved in the process of carcinogenesis, tumor growth, and invasiveness, and the patterns of tumor–host interactions." (PMID 32587587, 2020). "We identified Stat3, Irf7, Cox2, and Ifnβ as being up-regulated, while Il1β and Il12α show down-regulation under tumor condition." (PMID 32668709, 2020). "Pro-inflammatory cytokines, including TNF-α, IL-1α, IL-1β, and IL-6, in the tumor microenvironment have been reported to promote tumor progression, metastasis, and invasion." (PMID 33348858, 2020). "High plasma levels of IL-6, TNF-α, INF-γ, and IL-1β have been observed in both tumor-bearing animals and cachectic cancer patients." (PMID 31941005, 2020). "IL-1β was produced by monocytic MDSCs in the premetastatic lungs, promoted E-selectin expression, and led to tumor cell adhesion to the vascular endothelium." (PMID 33322216, 2020). "In different murine cancer models, the association of blocking Abs against CD39 and PD-1 slows tumor growth through a NLRP3/IL-18-dependent and IL-1β-independent mechanism." (PMID 33261061, 2020). "After tumorigenesis, IL-1β interacts with vascular endothelial growth factor (VEGF) in the tumor microenvironment to drive angiogenesis and enable tumor metastasis and diffusion." (PMID 33488930, 2020). "The analysis of IL-1β protein expression by immunohistochemistry in xenograft tumor showed that the expression of IL-1β protein was mainly localized to the cytoplasm in the xenograft Hep-2 cells." (PMID 32577124, 2020). "When gPTGS2 and IL1β levels were used to discriminate those CRC depending on IL1β for gPTGS2 expression (enriched in stromal gPTGS2) from tumors with an independent gPTGS2 expression (enriched in tumor gPTGS2), survival curves showed an immediate dichotomy." (PMID 32168749, 2020). "After blocking the effect of inflammasome activation by administration of YVAD‐CMK in vivo, the levels of capase‐1 and IL‐1β remarkably were reduced in tumour from Ad‐CAIXpromotor‐AIM2 group than Ad‐CAIXpromotor group." (PMID 32725966, 2020). "In these co-cultures of tumour cells and monocytes, we detected upregulation of cytokines (TNFα, MCP-1, IL-10, CXCL-10, IL-1β, IL-6, IL-23) associated with MOv18 IgE ADCC compared to isotype control-triggered cytotoxicity." (PMID 33203088, 2020). "By averaging z‐score expression levels per tumor, tumors with DDR mutation had lower expression levels of CTLA‐4, IFNG, TNF, FAS, and VTCN1, and higher expression levels of IL6, IL1B, and IL12A compared with the DDR wild‐type ones." (PMID 31991061, 2020). "In contrast, another study showed in the B16-F10 model that blocking IL-1β with an antibody increased tumor appearance in wild type (WT) mice, thus suggesting that IL-1β was protective in this context." (PMID 32635472, 2020). "It has been proven that tumor-derived soluble factors and IL-1β are important stimuli for the expansion and migration of MDSCs." (PMID 32825489, 2020). "IL-1β has been used for the treatment of solid tumors (given experimentally) reducing effects on tumor growth, and an increase of lymphocytes and inflammatory cells influx into the tumor." (PMID 33194476, 2020). "On the other hand, a trend towards increased release of other main cytokines, i.e., IL-12p40 and IL-1β, was detected in moDCs incubated with tumor supernatant from the highly cytotoxic condition, which can be associated with an immunostimulatory profile." (PMID 32326519, 2020). "Currently, accumulating studies have demonstrated that chronic inflammation related to cellular senescence plays a key role in tumor immunosuppression and major proinflammatory factors, including IL-1α, IL-1β, IL-6 and IL-8." (PMID 33232279, 2020). "In the CAC milieu, IL-1β produced by neutrophils can induce intestinal mononuclear phagocytes (MPs) to produce IL-6, thereby promoting tumour formation." (PMID 32760201, 2020).
tumor (continued). "IL-1β is also involved in promoting tumor aggressiveness by directly modulating the migration ability of both inflammatory and tumor cells through the regulation of the integrin superfamily." (PMID 32012917, 2020). "NLRP3 triggers innate immunity by activating caspase-1, then cleaves the inflammatory molecule IL-1β and IL-18, which induces inflammation and eliminate tumor cells." (PMID 33603669, 2020). "Cytokines, including interleukin-1β (IL-1β), IL-6, tumor necrosis factor-alpha (TNF-α), and chemokines were found to be highly expressed in tumor-associated inflammation." (PMID 33172072, 2020). "Inhibiting IL-1β restores tumor growth, while local administration of recombinant IL-1β inhibits tumor growth." (PMID 32635472, 2020). "The activation of neutrophils that produce IL-1β which leads to dendritic and macrophage produce IL-6, a cytokine that acts as a tumor promoter." (PMID 33369455, 2020). "Secretion of IL-1β by tumor cells and stromal CAFs leads to increased NF-κB activity in both cell types, increased intratumoral collagen deposition and chemoresistance." (PMID 32961746, 2020). "Recently, tumor-derived IL-1β was shown to foster an immunosuppressive TME by promoting M2 macrophage polarization and an influx of myeloid-suppressor cells, such as regulatory B and Th17 cells." (PMID 32961746, 2020). "Compared to traditional Th9 (Th9IL-4 + TGF-β) cells, Th9IL-4 + IL-1β cells show stronger cytotoxic effect and tumor killing ability, exerting a powerful antitumor effect in melanoma." (PMID 32228589, 2020). "Local overexpression of IL-1β in the early chronic inflammatory environment promotes tumor development." (PMID 33488930, 2020). "CTCs can modulate NK cell anti-tumor activity through production of inhibitory cytokines (e.g., IL-1β, IL-8, IL-10, and prostaglandin E2) that block the NK cell immunoglobulin receptors (KIRs)." (PMID 32260071, 2020). "Our data suggest that up-regulation of Gal-9 expression in NPC cells promotes MDSC expansion depending on IL-1β and IL-6 induction from tumor cell and myeloid cell itself." (PMID 32632113, 2020). "Notch signaling is involved in crosstalk with other oncogenic signaling pathways, including IL-1β and NF-κB, and plays a role in tumor survival and chemoresistance." (PMID 32899791, 2020). "Compared to that of MO mice, the level of IL-1β was significantly decreased in the tumours of CTX- and FLP-treated MO mice (P < 0.001 and P < 0.01, respectively)." (PMID 32308722, 2020). "Such set includes cytokines that use unconventional routes, as TGF-β and IL1-β, both responsible for playing antagonistic roles within the tumor microenvironment, depending on the cellular context." (PMID 33324568, 2020). "NLRP3 triggers innate immunity by activating caspase-1 and then cleaves immune and metabolic substrates, especially the pro-inflammatory cytokine interleukin-1β (IL-1β), which induces inflammation and promotes tumor growth." (PMID 32435622, 2020). "IL-1β and TNF-α induce VEGF-C expression in tumor-associated macrophages, hence promoting lymphangiogenesis and lymph node metastasis." (PMID 33172072, 2020). "In particular, IL-1β that is generated within the tumour microenvironment predominantly by tumour-infiltrating macrophages, can promote tumour growth and metastasis via different mechanisms." (PMID 32630302, 2020). "These cells, named activated (M2) macrophages, infiltrate tumor tissues and are the major source of inflammasome activation and IL-1β production." (PMID 32825489, 2020). "Lobaplatin effects against tumor cells were convincing, implying decrease of tumor cell viability, cell membrane damaging, and increased IL-1β levels." (PMID 33015196, 2020). "IL‐1β secretion is a marker of NLRP3 activation, which linked the tissue damages with tumor‐promoting inflammation." (PMID 32508035, 2020). "Another approach consists of amplifying the expression of CCL5 induced by IL-1β already present in the tumor microenvironment." (PMID 33194476, 2020).